EPHB6 (EPH receptor B6)
Diseases named in the same sentence as EPHB6 in open-access papers (continued):
Sharing a sentence is not in itself a finding about the gene and the disease.
melanoma (14 papers, 2010 to 2024). A malignant, usually aggressive tumor composed of atypical, neoplastic melanocytes. "Loss of EphB6 expression has been associated with augmented metastatic potential in different cancer types, such as non-small cell lung cancer, melanoma and colon cancer." (PMID 34943502, 2021). "Understanding the reasons for variable mutation frequency will lead to precise interventions to effectively target oncogenic mutations, such as in NRAS or EPHB6 in melanoma." (PMID 27191502, 2016). "EphB6 is a clinically significant Eph receptor, as indicated by its loss in the most aggressive forms of melanoma and neuroblastoma." (PMID 25789021, 2015). "For instance, mutations have been identified in EphA3 in melanoma and glioblastoma, and EphA3, EphA4, EphA7, and EphB6 in colorectal cancers." (PMID 20224755, 2010). "We also observed EPHB6 mutation-induced paclitaxel resistance in A375P melanoma and Huh7 liver cancer cells, which may indicate EPHB6 (Q926R) mutation-induced paclitaxel resistance in diverse cancer types." (PMID 31160603, 2019). "EPHB6 was down-regulated in several cancer types such as metastatic lung cancer, melanoma, and CRC, while high expression of SEMA4D promoted angiogenesis in many tumors." (PMID 37182141, 2023). "Hafner and colleagues studied melanomas and found that compared to benign moles, EphB6 mRNA expression decreased in melanoma and metastatic tumors." (PMID 33962392, 2021). "In particular, in NSCLC, melanoma, and triple-negative breast cancers, EphB6 overexpression increased adhesiveness to the substrate impairing migratory potential." (PMID 33802447, 2021). "Overall, these data suggest that melanomas from geographically different regions in NZ have markedly different mutation frequencies, in particular in the NRAS and EPHB6 genes, when compared to TCGA or other populations." (PMID 27191502, 2016). "EPHA1, EPHA3 and EPHB6 were contained in regions of copy gain, suggesting their oncogenic role during melanoma progression." (PMID 27095580, 2016). "Previous studies observed that expression of EphB6 was diminished or lost in the most aggressive forms of melanoma and neuroblastoma." (PMID 25789021, 2015). "Mutations in EPHA3 have been detected in melanoma, and several ephrin-derived peptide antigens (from EPHA2, EPHA3 and EPHB6) can be recognized by cancer-specific cytotoxic T-cells." (PMID 21494657, 2011). "On the other hand, also downregulation of Eph receptors can lead to increased metastasis and carcinogenesis as shown for EphA1 in colorectal cancer, EphA7 in prostate carcinomas, and EphB6 in melanoma." (PMID 20224755, 2010). "In several malignancies, an inverse correlation between EphB6 expression and solid tumor aggressiveness was observed; these include melanoma, neuroblastoma, colorectal and prostate cancers, thereby suggesting that EphB6 is capable of suppressing invasive and metastatic phenotypes." (PMID 34360976, 2021). "Mutations in EPHB6 have been observed recurrently in other cancer types such as non-small cell lung cancer, but to our knowledge our study is the first to identify recurrent EPHB6G404S mutations in melanoma." (PMID 27191502, 2016).
colorectal cancer (13 papers, 2010 to 2025). A primary or metastatic malignant neoplasm that affects the colon or rectum. "Our results indicate that the loss of EPHB6 contributes to the metastatic process of colorectal cancer." (PMID 28262839, 2017). "Several somatic mutations of the EPHB6 gene have been previously identified in lung cancer, colorectal cancer, ovarian cancer and glioma." (PMID 23226491, 2012). "Recent in vivo experiments have indicated that EphB6 deficiency may be a contributing factor to the development of colorectal cancer (CRC) tumors." (PMID 40900801, 2025). "EphB6 is a tyrosine kinase receptor that has been implicated in colorectal cancer (CRC)." (PMID 40900801, 2025). "EphB6 expression was discovered to be lower in colorectal cancers in contrast to adenoma and healthy tissues, and its loss promotes tumour progression, since EphB6 knockdown elevated lung metastasis in mice, whereas reintroducing EphB6 into colon cancer cells substantially lowered metastases." (PMID 36830852, 2023). "Ephb6 with APC mutation is found to be overexpressed in colorectal cancer." (PMID 32993565, 2020). "We next investigated whether the expression of EPHB6 was associated with the survival or other clinicopathological features of patients with colorectal cancer." (PMID 28262839, 2017). "Another study on colorectal cancer, found that decreased EphB6 expression correlated with decreased OS in cancer patients." (PMID 33962392, 2021). "First, we assessed the levels of EPHB6 mRNA and protein expression in a panel of 25 colorectal cancer cell lines." (PMID 28262839, 2017). "EphB6 is upregulated in human colorectal cancer (CRC) tissues as compared to normal tissues, and its overexpression promotes proliferation, migration and invasion by IMCE colorectal adenoma cells, in which one Apc allele is mutated." (PMID 27145271, 2016). "Moreover, reduced EPHB6 expression was observed in lymph node metastases compared to primary tumors of patients with locally advanced colorectal cancer." (PMID 28262839, 2017). "Germline alterations have previously been described for EPHB6 in familial colorectal cancer To date, the functional consequences of these genetic alterations on a cellular level are unknown." (PMID 23226491, 2012). "In flow cytometry, Eb6Mab-3 demonstrated reactivity with EphB6-overexpressed Chinese hamster ovary-K1 cells (CHO/EphB6) and endogenously EphB6-expressing DLD-1 colorectal cancer cells." (PMID 40065768, 2025). "These included PRSS2, EPHB6 and FABP4, which showed correlation with colorectal cancer prognosis, whereas high expression of these genes was related to poor prognosis." (PMID 32033604, 2020). "This would be consistent with the lack of prognostic value observed here for EPHB6 tumor levels in a stage-specific cohort of colorectal cancer patients." (PMID 28262839, 2017). "EPHB6 expression levels were assessed by immunohistochemistry of sections of a tissue microarray containing formalin-fixed, paraffin-embedded (FFPE) tumor samples from a cohort of 130 colorectal cancer patients with locally advanced disease (Dukes C)." (PMID 28262839, 2017). "However, the role of EPHB6 in colorectal cancer has not been investigated." (PMID 28262839, 2017).
non-small cell lung carcinoma (10 papers, 2012 to 2025). A group of at least three distinct histological types of lung cancer, including non-small cell squamous cell carcinoma, adenocarcinoma, and large cell carcinoma. "In humans, EPHB6 is implicated in inhibition of metastasis in several types of cancer, including non-small cell lung cancer." (PMID 34315444, 2021). "Our results suggest that EPHB6 mutations promote metastasis in a subset of patients with non-small cell lung cancer." (PMID 23226491, 2012). "The current study was conducted to screen for the occurrence and to identify functional consequences of EPHB6 mutations in non-small cell lung cancer." (PMID 23226491, 2012). "In current study we identified mutations of EPHB6 as a pro-metastatic feature in non-small cell lung cancer." (PMID 23226491, 2012). "However, EPHB6 mutations were also proved to promote metastasis in a subset of patients with non-small cell lung cancer." (PMID 27463019, 2016). "Taken together, mutations in EPHB6 occurring in non-small cell lung cancer might lead towards a pro-metastatic phenotype." (PMID 23226491, 2012). "While EPHB6 is amplified in our cohort, its function is known to be a metastasis suppressor in non-small cell lung cancer, suggesting that it has a different function in colon tissue that needs to be characterized further." (PMID 22879877, 2012). "Here, we sequenced the entire coding region of EPHB6 in 80 non-small cell lung cancer patients and 3 tumor cell lines." (PMID 23226491, 2012). "In line, EPHB6 is the receptor tyrosine kinase for which low expression was most closely related with poor prognosis in early stage non-small cell lung cancer." (PMID 23226491, 2012). "EphB6 serves as an oncogene which involved in the development and malignancy of tumors, including colon, leukemia, tongue squamous cell carcinoma, breast, bladder, and non-small cell lung cancer (NSCLC)." (PMID 40065768, 2025). "Notably, EPHB6 suppresses metastasis in non-small-cell lung cancer." (PMID 32754286, 2020).
neuroblastoma (9 papers, 2014 to 2024). Neuroblastoma (NB) is the most common solid, extracranial childhood tumor. "In neuroblastoma patients, the expression of EphB6, ephrin-B2, and ephrin-B3 in tumors has been associated with a positive prognosis." (PMID 38811954, 2024). "In their first study, they identified the expression of EPHB6, ephrin-B2, and ephrin-B3 in neuroblastoma cells, correlating with a favorable prognosis." (PMID 38612645, 2024). "Specifically, the observation that a high expression of EPHA2 in neuroblastoma, EPHB1 in glioma, EPHB6, ephrin-B2, and ephrin-B3 in neuroblastoma correlates with a better prognosis is in line with a tumor-suppressive role of these EPHs." (PMID 38612645, 2024). "Among the favorable neuroblastoma genes examined (EPHB6, EFNB2, EFNB3, TrkA, CD44, MIZ-1), S(+)-ibuprofen augmented the expression of EPHB6 significantly in four of five neuroblastoma cell lines tested." (PMID 24173829, 2014). "Additionally, ectopic expression of EphB6 has shown the ability to suppress the malignant phenotype of neuroblastoma cell lines." (PMID 38811954, 2024). "In addition, S(+)-ibuprofen enhanced the expression of some favorable neuroblastoma genes (EPHB6, CD44) and genes involved in growth suppression and differentiation (EGR1, EPHA2, NRG1 and SEL1L)." (PMID 24173829, 2014). "Furthermore, forced expression of EphB6 in neuroblastoma cells may decrease their tumorigenicity in mouse xenograft models." (PMID 25789021, 2015). "Neuroblastoma, medulloblastoma, and rhabdomyosarcoma are characterized by increased EPHB4 expression, while T-ALL presents enhanced EPHB6 expression." (PMID 38612645, 2024). "On the other hand, high expression levels of EPHA2 in neuroblastoma, of EPHB1 in glioma, and of EPHB6, ephrin-B2 and ephrin-B3 in neuroblastoma confer a better prognosis." (PMID 38612645, 2024).
colon cancer (6 papers, 2017 to 2025). "Importantly, we found that the reintroduction of EPHB6 into EPHB6-deficient cells significantly reduced the metastatic growth of colon cancer cells in the lungs of immunocompromised NOD/SCID mice after tail-vein injection." (PMID 28262839, 2017). "The top downregulated genes included protease inhibitor Itih2, glycosyltransferase B3gnt5, as well as Eph receptor 6 (Ephb6) and phospholipase Pla2g4c, found to be overexpressed in a colon cancer cell line and human colon cancer tissues." (PMID 40631899, 2025). "Reintroduction of EPHB6 into LIM2405 colon cancer cells resulted in a significant reduction in the number of lung metastases observed in NOD/SCID mice compared to animals injected with the control EPHB6-deficient cells (LIM2405-EV)." (PMID 28262839, 2017). "When considered together, these results indicate that EPHB6 regulates the metastatic potential of colon cancer cells." (PMID 28262839, 2017). "Therefore, an experimental animal model of metastasis was used to directly investigate the possible role of EPHB6 in the late stages of metastatic spread of colon cancer cells." (PMID 28262839, 2017). "Moreover, EPHB6 knockdown in SW480 colon cancer cells significantly increased the number of metastatic lesions observed in the lungs of NOD/SCID mice 52 days after tail-vein injection." (PMID 28262839, 2017). "However, reintroduction of EPHB6 into colon cancer cells significantly reduced the number of lung metastasis after tail-vein injection in immunodeficient mice, while EPHB6 knockdown in EPHB6-expressing cells increased their metastatic spread." (PMID 28262839, 2017). "Moreover, ectopic expression of EPHB6 in EPHB6-deficient colon cancer cells or downregulation of EPHB6 in cell lines with endogenous expression did not affect their anchorage-independent growth on a semi-solid substrate." (PMID 28262839, 2017). "Although EPHB6 does not regulate the motility or growth of colon cancer cells in vitro, the loss of this EPH receptor could regulate tumor initiation and/or progression in the more complex context of the whole organism." (PMID 28262839, 2017). "Collectively, these results demonstrate that EPHB6 does not regulate the motility, anchorage dependence or proliferation of colon cancer cells." (PMID 28262839, 2017). "We found that EPHB6 does not regulate the growth of colon cancer cells, either on a solid substrate, a semisolid substrate or when grown as subcutaneous xenografts in immunodeficient mice." (PMID 28262839, 2017). "However, we found here that the motility of colon cancer cells was not affected by the modulation of EPHB6 levels in four independent tumor cell lines, indicating that this function of EPHB6 in cancer cells is context-dependent." (PMID 28262839, 2017).
lung carcinoma (5 papers, 2012 to 2023). "Loss of EPHB6 function by decreased expression or mutational inactivation might therefore contribute to lung cancer metastasis." (PMID 23226491, 2012). "Furthermore, certain methylation markers, such as DAL-1, EPHB6, HS3ST2, TMEM88 and MGMT, specifically associated with lung cancer progression and metastasis, were found to have increased methylation levels." (PMID 37506102, 2023). "EPHB6 might play an important role in lung cancer metastasis given that it is frequently epigenetically silenced and/or mutated in a significant fraction of patients." (PMID 23226491, 2012). "This makes it possible that EPHB6 is a relevant modifier of metastatic capacity in lung cancer." (PMID 23226491, 2012). "PI3Kα inhibitor DFX24 shows antiproliferation and apoptosis of lung cancer cells by inhibiting PI3K/AKT and ERK but promoting EPH receptor B6 (EPHB6) expression." (PMID 36139919, 2022).
adenoma (4 papers, 2016 to 2024). A neoplasm arising from the epithelium. "APC was progressively downregulated and EphB6 was upregulated as disease progressed toward adenocarcinoma, but both were highly expressed in adenomas." (PMID 27145271, 2016). "In summary, using an EphB6 mouse knockout model we found that the loss of EphB6 does not initiate intestinal tumorigenesis and is not involved in the early tumor progression through the adenoma-to-carcinoma transition." (PMID 28262839, 2017). "However, the mouse models used here develop mostly benign adenomas and are not ideally suited for investigating the role of EPHB6 in the later stages of tumor development." (PMID 28262839, 2017).
Hypertension (4 papers, 2017 to 2020). The presence of chronic increased pressure in the systemic arterial system. "Our study with stratification of testosterone levels has enhanced the association of variants of molecules in the EPHB6 signaling pathway with hypertension risks and revealed the association of a CHRNA3 variant with hypertension risks." (PMID 33329690, 2020). "These patients had augmented chances of having detrimental variants in the EPHB6 signaling pathways (including AChR subunits) due to their hypogonadic condition because hypertension was only revealed in castrated Ephb6 KO mice." (PMID 33329690, 2020). "To assess the relevance of this phenotype to human hypertension, in this study we investigated the association of SNPs in the EPHB6 gene, and in the genes of its two ligands, EFNB1 and EFNB3, with hypertension in Han Chinese hypogonadic males." (PMID 30262919, 2018). "There is a possibility that nAChR might be involved in EPHB6 signaling, and thus sequence variants of its subunit genes are associated with hypertension risks." (PMID 33329690, 2020). "However, in the age of personalized medicine, for those whose hypertension is caused by EPHB6 mutations and subsequent hypogonadism, if testosterone could address the cause rather than symptoms, its therapeutic application should be considered." (PMID 29339804, 2018). "This prior knowledge plus our current findings from the human genetic study and mouse AGCC experiments allow us to propose the following model for the implication of the regulation of AGCC function by CHRNA3 and EPHB6 in human hypertension pathogenesis." (PMID 33329690, 2020). "Our previous animal study demonstrates that castrated EPHB6 KO mice exhibit hypertension, suggesting that EPHB6 and/or its signalling pathways are involved in testosterone-dependent blood pressure control." (PMID 30262919, 2018). "We previously demonstrated that EPHB6 KO in castrated mice led to hypertension." (PMID 33329690, 2020). "This is evidenced in our previous report that the castrated EPHB6 KO mice presented hypertension." (PMID 33329690, 2020). "Why were SNPs in the EFNB3 gene but not the EPHB6 gene significantly associated with hypertension in hypogonadic males, in spite of the EPHB6 KO leading to hypertension in castrated mice?" (PMID 30262919, 2018). "To assess whether this finding in mice is relevant to human hypertension, we conducted a human genetic study for the association of EPHB6 and its two ligands, EFNB1 and EFNB3, with hypertension in hypogonadic patients." (PMID 30262919, 2018). "Thus, we speculated that EFNB1 and EFNB3 are more relevant to EPHB6 signalling for the hypertension phenotype, and hence they were included in our current hypertension association study." (PMID 30262919, 2018). "The deletion of EPHB6, EFNB1 and EFNB3 all result in hypertension in mice, while the deletion of EFNB2 leads to an opposite phenotype, i. e., hypotension." (PMID 30262919, 2018). "EPHB6 gene knockout (KO) in mice leads to hypertension in castrated males but not in un-manipulated KO males or females." (PMID 30262919, 2018). "Any defect in these signalling pathways could lead to the hypertension phenotype, while EPHB6 itself might not be critically important." (PMID 30262919, 2018).
invasive breast carcinoma (4 papers, 2011 to 2024). A carcinoma that infiltrates the breast parenchyma. "EphB6 has previously been characterized as a signature molecule for invasive breast carcinoma cells." (PMID 21811619, 2011). "One study on Eph receptors and invasive breast carcinoma suggested that the level of FKBP1A was significantly affected by EphB6, which was a target mRNA of miR-100, the changes in miRNAs and the target mRNA may have a role in PI3K/Akt/mTOR pathways." (PMID 32497068, 2020). "To achieve this, we developed a co-culture system in which fluorescently labeled EphB6 and ephrinB1 were expressed in different sublines of the MDA-MB-231 invasive breast cancer cell line." (PMID 38627519, 2024). "All EphB6 constructs were expressed in the MDA-MB-231 invasive breast cancer cell line, which does not endogenously express EphB617,19." (PMID 38627519, 2024).